IL6 (interleukin 6)
Diseases named in the same sentence as IL6 in open-access papers (continued):
Sharing a sentence is not in itself a finding about the gene and the disease.
tumor (continued). "The fact that IL-6 and IL-8 represent rather unspecific inflammatory cytokines, which most likely reflect high tumor regeneration and proliferation capacity, could imply that these markers are rather method specific for TACE therapy and less tumor specific." (PMID 29899223, 2018). "However, irradiated tumor cells that showed approximately 30 to 35% of apoptosis, inhibited DCs maturation through the downregulation of MHC II and CD 86 expression as well as suppression of IL-12, TNF α and IL-6 release." (PMID 30081891, 2018). "Interestingly, we have also described here that oleuropein alone or in combination did not modify tumor growth in this animal model and that even promotes a pro-inflammatory status increasing IL-6 and TNFα production." (PMID 29373553, 2018). "In particular, CAFs differentiation can be induced by tumour cell-derived transforming growth factor β (TGF-β), epidermal growth factor (EGF), PDGFα, PDGFβ, basic fibroblast growth factor (bFGF, also known as FGF2), interleukin 6 (IL-6), and interleukin 1β (IL-1β)." (PMID 29967776, 2018). "In vivo information from murine models of TN-BC showed different response to STAT3 pathway blocking in vitro vs in vivo (i.e. IL-6 pathway inhibition did not influence tumour cell proliferation in vitro but potently reduced tumour growth using TN models of murine BC in vivo)." (PMID 29256156, 2018). "However, direct regulation of lactate and other possible soluble factors, such as PDGF, SDF-1, and IL-6, was not assayed in the present study, which points the way for further investigation of detailed mechanisms involved in the tumor-stroma interaction." (PMID 29854071, 2018). "Specifically, proinflammatory cytokine IL-6 induces Twist1 expression in normal fibroblasts via STAT3 phosphorylation, and Twist1 then promotes the transdifferentiation of normal fibroblasts to CAFs via activation of a strong tumor-promoting chemokine, CXCL12, as well as suppression of senescence." (PMID 29029429, 2017). "At the same time, there were more TNF-α and IL-6 positive cells in tumor-adjacent tissues than that in control lung tissues, which suggests that tumor-adjacent cells surrounding the adenocarcinoma may also contribute to TNF-α and IL-6 production." (PMID 28801561, 2017). "IL-6 expression was not statistically different in tumor tissues compared to control samples." (PMID 29299026, 2017). "Potentially, the induction of IL-6 by NO, maybe dependent on other factors present in the tumor microenvironment but absent in an in vitro setting." (PMID 29113326, 2017). "Consistently, compared to naive mice, the serum levels of G-CSF and IL-6 in cir-B16F0-mice were elevated, which further demonstrated that the function of neutrophils could be converted to tumor-promoting by circulating tumor cells." (PMID 28415700, 2017). "In this respect, Pries and colleagues could show that HNSCC tumor cell lines alone could secrete high levels of IL-6/IL-8 but no significant levels of IL-4 and IL-10 in the absence of infiltrating immune cells." (PMID 28443091, 2017). "Moreover, IL-1 stimulates interleukin-6 (IL-6) production by macrophages, a pro-inflammatory cytokine that activates CD4+ T cells and macrophages, induces immune cells recruitment, generates epithelial cells proliferation and favors tumor growth." (PMID 28437455, 2017). "IL-6, STAT3 and HIF1 mRNA levels in Hep2-CSC were significantly increased as compared to the IL-6, STAT3 and HIF1 mRNA expression levels in Hep2 cells and Hep2-derived tumor tissue, which were obtained from the tumor tissue after Hep2-cells were injected into dorsal area of nude mice (p < 0.001)." (PMID 28878571, 2017).
tumor (continued). "Because IL-6 was the cytokine most abundantly secreted from DCIS-CAF cocultures, we investigated whether the tumor-suppressing effects of MEPs on DCIS in the presence of CAFs (i.e., reduced cell growth, ECM proteolysis, and invasion) were a result of decreased IL-6 secretion." (PMID 28506312, 2017). "However, these CSC markers were not upregulated in IL-6 knockdown cells and in IL-6 knockdown cell-derived tumor tissue." (PMID 28878571, 2017). "The combined treatment of TNF-α and IL-6 could induce morphological changes in A549 cells, characterized by fibroblast-like cells, while AFG1 did not cause EMT in the tumor cells." (PMID 28801561, 2017). "Our current study clearly demonstrated that inflammation can also act as an “ignitor” to autonomously initiate de novo tumor development without other genomic insults, in which context the pro-inflammatory cytokine IL-6 serves as a critical mediator or “lynchpin”." (PMID 28077171, 2017). "For IL-6 we could however observe an early decrease in BAT and SC tissue, while IL-8, MCP-1, MIP1-a and MIP1-b showed an increase in BAT and SC tissue, although the increase was somewhat delayed compared to the increase in tumor tissue." (PMID 27664151, 2017). "Interestingly, CM derived from HuH7, PT-7, PT-12 and PT-19 showed high levels of IL-6 and angiogenin while the CM from the HC-PT-5 tumor did not present these cytokines." (PMID 29113298, 2017). "Our data suggests that HNSCC tumor cells production of PDGF-AA and IL-6 may be responsible to the increased tropism of MSC to the tumor site, which lays the foundation for further study in the MSCs in this context and the development of novel cellular/chemokines targeting therapies for this cancer." (PMID 27931212, 2016). "Taken together, our findings suggest that IL-6 is a potential treatment target for OSCC, improving the outcomes of chemoradiotherapy and prognosis of patients with OSCC by operating on the local and systemic inflammatory response initiated by tumor- and/or stromal cell-derived IL-6." (PMID 26812901, 2016). "We show that ICAM-1 is upregulated in OS CSC exposed to non-tumor component, but could not confirm previous data showing its dependency on IL-6." (PMID 27851822, 2016). "Therefore, IL-6 and its activated STAT3 pathway may represent effective targets for blocking tumour self-seeding by CTCs." (PMID 26623559, 2016). "Interestingly, these tissue specific changes occurred independent to total tumor number and circulating IL-6 levels, which were not affected by PDTC treatment." (PMID 27449092, 2016). "As the aggregated tumor cells were suggested to bear higher metastatic ability than non-aggregated cells, we believe the IL-6 regulation of aggregation of CD133+ cells may also have a clinical significance and further studies are thought to be necessary." (PMID 26675547, 2016). "Similarly, an inhibitor of phosphatidylinositol-3-kinase (PI3K)/AKT/mammalian target of rapamycin (mTOR) pathway, NVP-BEZ235, inhibited TME-specific signaling pathways such as IL4 and IL6/STAT3, resulting in suppression of angiogenesis, migration, and tumor invasiveness in MCL cells." (PMID 27119356, 2016). "Moreover, wogonoside inhibited the mRNA levels of IL-1β, IL-6 and TNF-α in tumor tissues." (PMID 27102438, 2016). "Increased IL-6 after 5-FU C3 might help to promote chronic inflammation and residual tumor survival, which was a negative factor in anti-tumor responses." (PMID 27645787, 2016). "Cytokines, such as IL-6, may then activate STAT3 to promote tumor growth." (PMID 27148488, 2016).
tumor (continued). "We found significantly retarded tumor growth in xenografts derived from CD133+ cells isolated from the A549IL-6si cell line compared to xenograft tumors derived from the CD133+ cells of the A549sc cell line, supporting that intrinsic IL-6 stimulated CD133+ cell growth in xenograft tumors." (PMID 26675547, 2016). "However, here we observed a significant decrease in both tumor tissue and circulating levels of IL-6, but with no beneficial effects on skeletal muscle." (PMID 28149280, 2016). "CTCL tumor cell lines, but not non-malignant cell lines, produce IL-6 spontaneously." (PMID 27780938, 2016). "This study first reported that IL-6 treatment could prevent the painful behavior of CIPN without interfering with the anti-tumor activity of these chemotherapeutic regimens, suggesting a potential neuroprotective effect of IL-6 on CIPN." (PMID 27267059, 2016). "Exposure to hPSC-CM significantly increased the size of colonies formed while blockade of IL-6 with the neutralizing antibody significantly reduced hPSC-CM induced colony size to baseline levels (p<0.05), suggesting that PSC secreted IL-6 plays a role in supporting tumor growth." (PMID 27602757, 2016). "Furthermore, WCUP decreased the CT-26 cell-derived production of IL-6 and myostatin, by which WCUP-treated CT-26 CM showed less impairment of C2C12 myoblast proliferation and differentiation and prevention of tumor-induced C2C12 myotube wasting, compared with WCUP-untreated control CT-26 CM." (PMID 27064118, 2016). "These pro-tumorigenic cytokines include interleukin (IL)-6, IL-11, IL-21 and IL-22 that activate the STAT3 transcription factor; TNFα, IL-1 and IL-18 that activate NF-κB; and the IL-23 to IL-17 axis of inflammation that activates both STAT3 and NF-κB in tumor cells." (PMID 31051015, 2016). "These tissue specific responses were independent of total tumor number and circulating IL-6." (PMID 27449092, 2016). "IL-6 levels in the Selumetinib group were not significantly different from non-tumor bearing mice." (PMID 28149280, 2016). "Increased metastasis in EMT6 tumor bearers was seen in vivo following adoptive transfer of serum, or serum‐derived exosomes, from 4THM tumor bearers, an effect which was attenuated by anti‐IL‐6, and anti‐IL‐17, but not anti‐TNFα, antibody." (PMID 26725371, 2016). "Our results indicate that recombinant sgp130 by specifically blocking the IL-6 trans-signaling pathway, might have strong effects on HCC at various stages of the tumor development and could potentially be a valuable therapeutic agent for treating HCC in humans." (PMID 27080032, 2016). "Whether activated by cytokines such as IL-6, stressors like reactive oxygen species or driven by the progression towards castration resistance, STAT3 activation plays a vital role in the self-renewal and tumor-propagating capacity of PCSCs." (PMID 25595909, 2015). "Hence, the observed reductions of TGFβ, FGF2, IL-6 and HGF can not only be due to the reduction of tumor-infiltrating CAFs but also due to quantitative and/or qualitative changes in other intratumoral cell populations such as reduced numbers of ECs due to an anti-angiogenic effect of the treatments." (PMID 25849942, 2015). "Six days after tumour challenge, young mice in which donor OT-II cells had been primed, induced OVA-specific CD8+ T cells in tumour-draining LNs and in tumour more efficiently than mice possessing naive OT-II cells without DC vaccination, regardless of anti-IL-6 Ab treatment." (PMID 25850032, 2015). "In conclusion, the Nidus Vespae decoction could promote the proliferation of human PBMC, enhance the tumor cell-killing activity of CTL, elevate the IgG production of B cells, and strengthen the tumor cell phagocytosis as well as the cytokines (TNF-α and IL-6) production of monocytes." (PMID 26339270, 2015).
tumor (continued). "Large amounts of transmitters, such as M-CSF, IL-6, IL-10, TGF-β, and COX-2, induce transformation of TAMs into M2 macrophages that secrete immune inhibitory chemokines with poorer antigen presenting and cytotoxic abilities, leading to tumor growth and metastasis." (PMID 26167490, 2015). "Western blots of the tumor tissues retrieved from the mice at the end of the experiments revealed that tocilizumab, but not paclitaxel, inhibited the main downstream effector of IL-6 signaling, i.e. phosphorylated STAT3." (PMID 26287605, 2015). "Interestingly, 24 h after tasquinimod exposure, mRNA expression of different angiogenic factors (Vegfc, Nrp-1, Fgf2, Il-6) was decreased in MCH-IIhigh macrophages compared to vehicle TAMs, suggesting that M1 macrophages contribute to tumor vasculature shrinkage." (PMID 26673090, 2015). "Supporting this hypothesis, there was a positive correlation between IL-6 serum level and tumor size irrespective of gender." (PMID 25645622, 2015). "The elaborate cross-talk between macrophages, MDSCs, and tumor cells result in differential production of IL-6, IL-10, TNF-α, and NO, suggesting that the interaction between these cells has the potential to significantly alter the inflammatory milieu within the tumor microenvironment." (PMID 26052505, 2015). "Oral intake of mushroom beta-glucan in tumor-bearing mice demonstrated an increase in the gene expression of IL-12 and IFN-γ in tumor tissues and a decrease in serum TGF-β concentration and gene expressions of IL-6, IL-10, COX-2, and TGF-β in the tumor microenvironment." (PMID 26167490, 2015). "Since IL6 cytokine is also expressed in immune cells, xenografts from immune-deficient mice may not faithfully reflect the in vivo significance of SRF–YAP–IL6 signalling in tumour initiation." (PMID 26671411, 2015). "IL-6 was upregulated in both tumor and adjacent non-tumor tissues compared to normal tissues." (PMID 26547929, 2015). "It is known that, in addition to STAT3, cytokines like IL-6 and IL-10, VEGF, and Oncostatin M are able to activate other pathways such as PI3K/AKT and Ras/MAPK that govern fundamental processes, such as cell proliferation, differentiation, metabolism, and tumor survival." (PMID 25695042, 2015). "The partial response to a leptin-blocking peptide is in agreement with Coward and colleagues’ finding that siltuximab treatment (an anti-IL6 antibody) significantly reduces tumor burden, but does not completely eliminate metastatic foci and ascites accumulation in xenograft mouse models." (PMID 26053184, 2015). "Furthermore, the functional interplay of NOX4 and IL-6 in enhancing growth and survival of NSCLC cells in vivo was also confirmed by Ki67 (the biomarker to evaluate tumor proliferation) and TUNEL staining analysis (evaluation of tumor apoptosis)." (PMID 25504436, 2015). "Although the presence of CAFs in ascites tumors is not an obvious finding, in the current experimental model, IL-6 could be responsible for the cross talk between CAFs or phenotypically similar cells and tumor cells." (PMID 26347589, 2015). "Finally, tumor-derived prostanoids directly induce the production by myeloid cells of known cancer-promoting factors such as IL-6, CXCL1, and G-CSF, effectively shifting the tumor microenvironment from one favorable to tumor eradication to one that has pro-tumor activity." (PMID 26343581, 2015). "Importantly, BV6 significantly increased the secretion of IL-8, IL-6, granulocyte–macrophage colony-stimulating factor (GM-CSF) and monocyte chemoattractant protein-1 (MCP-1) from tumor cells into the supernatant, whereas IL-10 and VEGF remained largely unchanged (data not shown)." (PMID 25501823, 2014). "However, the effect of endothelial cell-secreted IL-6 on tumor cell STAT3 and overall tumor growth is not known." (PMID 24533454, 2014).
tumor (continued). "Also, IL-6 directly induces tumor growth and spread after triggering the canonical JAK/STAT pathway, as well as the SHP-2 driven Ras-Raf-MAPK signaling pathway and tumor angiogenesis." (PMID 24886605, 2014). "Furthermore, other factors released by tumor stroma components like IL-8, GRO, IL-6, or CCL-2 could also be involved in MSC recruitment to HCC." (PMID 25147818, 2014). "TGF-β increases the expression of PTHrP and other growth factors like IL-1, IL-6, IL-8, IL-11, prostaglandin E-2 (PGE2), macrophage colony stimulating factor (M-CSF), and tumor necrosis factor α (TNF-α) by direct impact on cancer cells, resulting in enhanced tumor growth in BM." (PMID 25147739, 2014). "Given the importance of IL-11 in promoting tumour initiation and development, and IL-6 in facilitating local polymorphonuclear infiltration in the gp130757FF mouse, it is significant that WP1066 effectively reduced the expression levels of both cytokines coincident with reversal of tumour growth." (PMID 24804649, 2014). "The failure to induce IL-6 secretion in tumor derived PMN, and the suppressed IL-6 release from LPS stimulated PMN from healthy controls cultured in supernatants from FaDu cancer cells may therefore be a tumor induced immune evasive mechanism to attenuate the effective anti-tumoral T cell responses." (PMID 24466243, 2014). "Although the role of IL-6 in lipolysis is not well established, a recent study has shown enhanced IL-6 signaling in brown adipose tissue in cachectic tumor-bearing mice suggesting that it may play a direct role in the activation of thermogenesis." (PMID 24624094, 2014). "Notably, expression of IL-6 is higher in endothelial cells than in the tumor cells themselves (data not show)." (PMID 24533454, 2014). "Interestingly, we observed that IL-6 and IL-8 were only expressed in the stroma and not in the tumor cells." (PMID 24885636, 2014). "Importantly, IRF1 depletion impedes BV6-stimulated secretion of additional proinflammatory cytokines such as granulocyte–macrophage colony-stimulating factor (GM-CSF), IL-8, IL-6 and monocyte chemoattractant protein-1, and migration of primary monocytes to BV6-treated tumor cells." (PMID 25501823, 2014). "Interestingly, 83.3% of CXCR2 positive/IL-8 negative cases exhibited IL-6 immunoreactivity, implying a redundancy of the angiogenic mechanisms in this tumor." (PMID 24593195, 2014). "When compared to tumor of origin IL-6 expression was significantly elevated (10-106 fold) in the CD49f−CD24−(MM) population and a majority of CD49f+CD24−(PM) populations, while significantly decreased an average 100 fold in the CD49f+CD24+(PP) populations when compared to tumor." (PMID 25269750, 2014). "Thus, these on-and-off results for HOXB9 expression and neutralizing antibodies suggest our hypothesis that bevacizumab inhibits HOXB9 induced tumor proliferation by silencing microenvironmental cytokine release including VEGF and IL6." (PMID 24885802, 2014). "Thus, in the tumor microenvironment, carcinoma-derived IL-1 (IL-1α and IL-1β) activates mesenchymal stem cells (MSCs) to produce PGE2 and other cytokines, such as IL-6, IL-8, Gro-α, and RANTES that in turn act on the carcinoma cells and induce activation of β-catenin and transition into CSCs." (PMID 23847618, 2013). "Therefore, it is perhaps not surprising that IL-6 knockdown, genetic ablation, or treatment with a neutralizing IL-6 antibody inhibits tumor growth in vivo." (PMID 24260500, 2013). "The tumor-promoting role of IL-6 may be exerted via MMP-2, whose production is increased by IL-6." (PMID 24023566, 2013). "Tumor cells themselves and the surrounding normal cells have the ability to secrete TNF-α that is a strong promoter of interleukin (IL)-6, another cytokine, that influences ERK/MAPK signaling pathway and thus, may show anti-proliferative and pro-apoptotic effect in PC-3 cell." (PMID 24168453, 2013).